VDAC1P11 (voltage dependent anion channel 1 pseudogene 11)
Gene: Processed pseudogene on chromosome 9 (94,287,699 to 94,288,550, reverse strand). Ensembl gene ENSG00000237679.
Diseases named in the same sentence as VDAC1P11 in open-access papers:
VDAC1P11 is named in the same sentence as 1 disease in open-access papers, as found by Europe PMC text mining. Sharing a sentence is not in itself a finding about the gene and the disease. The quoted sentences say what the papers report.
tumor (1 paper, 2023). "Interestingly, only the pseudogenes VDAC1P8 and VDAC1P11, upregulated in AML, have binding sites for transcription factors involved in development of the tumor counterpart." (PMID 37344914, 2023).